ARSA (arylsulfatase A)
Diseases named in the same sentence as ARSA in open-access papers (continued):
Sharing a sentence is not in itself a finding about the gene and the disease.
metachromatic leukodystrophy (continued). "Metachromatic leukodystrophy (MLD) is a lysosomal storage disorder (LSD) caused by an inherited deficiency of arylsulfatase A (ARSA; EC 3.1.6.8) (Gieselmann and Krägeloh-Mann, 2006)." (PMID 34093126, 2021). "Metachromatic leukodystrophy (MLD) is a rare neurodegenerative disease that results from a deficiency of the lysosomal enzyme arylsulfatase A (ARSA)." (PMID 33923989, 2021). "These lysosomal storage disorders (LSDs) are termed metachromatic leukodystrophy (MLD) and globoid cell leukodystrophy (also known as Krabbe disease) for the deficiency of ARSA and GALC activities, respectively." (PMID 34199863, 2021). "Metachromatic leukodystrophy (MLD) is an autosomal recessive LSD caused by mutations in the gene ARSA, encoding for the lysosomal enzyme Arylsulfatase A, which catalyses the conversion of sulfatide (sulfogalactosylceramide) in galactosylceramide." (PMID 33800050, 2021). "Homozygosity for ARSA mutations leads to severe ASA deficiency (<10%) that causes metachromatic leukodystrophy (MLD), a lysosomal storage disease that is inherited in an autosomal recessive manner with a reported frequency of 1:40000." (PMID 33036336, 2020). "Metachromatic leukodystrophy (MLD) is an autosomal recessively inherited sulfatide storage disease caused by deficient activity of the lysosomal enzyme arylsulfatase A (ASA)." (PMID 32632536, 2020). "In this context, recent studies have revealed the emerging role of arylsulfatase A (ASA), a lysosomal hydrolase encoded by the ARSA gene causing metachromatic leukodystrophy (MLD) in PD pathogenesis." (PMID 33036336, 2020). "Metachromatic Leukodystrophy (MLD) is a rare autosomal-recessive lysosomal storage disorder caused by mutations in the ARSA gene." (PMID 31186049, 2019). "Clinical trials with lentiviral transfected HSCs have been reported for the treatment of the brain in metachromatic leukodystrophy (MLD), an orphan disease of the brain caused by mutations in the gene encoding the lysosomal enzyme, arylsulfatase A (ASA)." (PMID 31998120, 2019). "Metachromatic leukodystrophy (MLD) is an autosomal recessive LSD caused by the deficiency of lysosomal arylsulfatase A (ARSA) enzyme." (PMID 30966479, 2018). "Metachromatic leukodystrophy (MLD) is an autosomal recessive lysosomal disorder due to ARSA gene mutations resulting in deficiency of the enzyme arylsulfatase A (ASA)." (PMID 28638987, 2017). "In the dysmyelinating disorder metachromatic leukodystrophy (MLD), arylsulfatase A deficiency leads to accumulation of sulfatide in lysosomes." (PMID 27141942, 2016). "Metachromatic leukodystrophy (MLD) is one of the rarest lysosomal disorders, caused because of arylsulfatase A enzyme deficiency." (PMID 26401154, 2015). "Metachromatic leukodystrophy (MLD) is a lysosomal storage disease caused by a functional deficiency in human arylsulfatase A (hASA)." (PMID 26283284, 2015). "Metachromatic leukodystrophy (MLD) is a rare, inherited neurodegenerative disease caused by deficiency of arylsulfatase A (ASA), or - more rarely - of its activator protein saposin-B." (PMID 24499656, 2014). "Metachromatic leukodystrophy (MLD) is caused by deficiency in arylsulfatase A (ASA) and accumulation of sulfated glycosphingolipids, predominantly 3-O-sulfogalactosylceramide (sulfatide)." (PMID 24307179, 2014). "Of relevance, an ARSA variant, p.P426L, a pathogenic MMV in metachromatic leukodystrophy, has been shown to selectively destabilize arylsulfatase A protein in lysosomes due to impairment of oligomerization." (PMID 40449593, 2025). "Metachromatic leukodystrophy (MLD) is an orphan genetic, neurodegenerative, and life-shortening disease due to pathogenic variants in the ARSA gene." (PMID 40410895, 2025).
metachromatic leukodystrophy (continued). "Metachromatic leukodystrophy (MLD) is an autosomal recessive neurodegenerative disorder caused by mutations in the arylsulfatase A (ARSA) gene, resulting in lower sulfatase activity and the toxic accumulation of sulfatides in the central and peripheral nervous system." (PMID 40536808, 2025). "Distinguishing metachromatic leukodystrophy from arylsulfatase A pseudodeficiency, present in about 1% of the general population, requires additional assessments such as urine sulfatide levels, radiolabeled sulfatide fibroblast loading, and DNA analysis." (PMID 38390857, 2024). "Metachromatic leukodystrophy (MLD; OMIM 250100 and 249900) is a rare lysosomal storage disease caused by deficient arylsulfatase A activity, leading to accumulation of sulfatides in the nervous system." (PMID 38494502, 2024). "The successful oligodendrocyte-based cell therapy was shown for pre-symptomatic arylsulfatase A (ARSA) null neonate mice, a murine model for human metachromatic leukodystrophy (MLD)." (PMID 38475854, 2024). "Another LSD with significant CNS involvement is metachromatic leukodystrophy (MLD), which is caused by mutations in the ARSA gene, leading to deficient activity of the enzyme arylsulfatase A (ARSA)." (PMID 39525762, 2024). "Metachromatic leukodystrophy, an autosomal recessive lysosomal storage disease, is characterized by a deficiency of arylsulfatase A (ARSA) due to a mutation in the arylsulfatase A gene on chromosome 22q13.3-qter." (PMID 38390857, 2024). "Metachromatic leukodystrophy (MLD, OMIM #250,100) is an inherited lethal neurometabolic disorder caused by deficiency of the lysosomal enzyme arylsulfatase A (ASA)." (PMID 38564053, 2024). "The sphingolipidoses Krabbe disease and metachromatic leukodystrophy are fatal early-onset demyelinating diseases caused by defects in the enzymes β-galactosylceramidase (GALC) and arylsulfatase A (ARSA) that degrade GalCer and sulfatide, respectively." (PMID 36996106, 2023). "Metachromatic leukodystrophy (MLD) caused by lysosomal abnormalities, which resulted from decreased activity of the enzyme arylsulfatase A and accumulation of aliphatic glucosinolates in the nervous system." (PMID 37170084, 2023). "Metachromatic leukodystrophy (MLD, MIM: 250100) is caused by the defect of arylsulfatase A (ARSA, EC: 3.1.6.1), a key enzyme in the catabolism of myelin-enriched sphingolipids." (PMID 36713078, 2023). "Metachromatic leukodystrophy (MLD) is an incredibly rare and disabling neurological condition in children caused by an enzyme defect in arylsulfatase A (ARSA)." (PMID 38264375, 2023). "Two LSDs, Krabbe disease, caused by deficiency of β-galactocerebrosidase (GALC), and Metachromatic leukodystrophy (MLD), caused by deficiency of arylsulfatase A (ARSA), belong to the class of leukodystrophies, manifesting with white matter pathology and progressive degeneration of myelin sheaths." (PMID 38163061, 2023). "Our patient #9, a 4 year old girl who was diagnosed with metachromatic leukodystrophy (MLD) (OMIM 250100), a sulfatide storage disease caused by deficient activity of the lysosomal enzyme arylsulfatase A (ARSA)." (PMID 37878632, 2023). "Metachromatic leukodystrophy (MLD; MIM:250100) is a rare autosomal recessive neurodegenerative disease caused by deficient sulfatide catabolism, due to mutations in the arylsulfatase A gene (ARSA)." (PMID 37480112, 2023). "Metachromatic Leukodystrophy (MLD) is a rare, autosomal recessive lysosomal storage disorder caused by a deficiency of the enzyme arylsulfatase A (ARSA)." (PMID 36329444, 2022). "Arylsulfatase A (ARSA) is a gene responsible for metachromatic leukodystrophy, an autosomal recessive lysosomal storage disorder." (PMID 35163450, 2022). "Metachromatic leukodystrophy (MLD) is a rare autosomal recessive lysosomal storage disorder caused by mutations in the ARSA gene leading to a deficiency of the enzyme arylsulfatase A (ARSA)." (PMID 36195888, 2022).
metachromatic leukodystrophy (continued). "Metachromatic leukodystrophy (MLD), a relentlessly progressive and ultimately fatal condition, is a rare autosomal recessive lysosomal storage disorder caused by a deficiency of the enzyme arylsulfatase A (ARSA)." (PMID 36195888, 2022). "Metachromatic Leukodystrophy (MLD) is a rare, autosomal recessive lysosomal storage disorder caused by a deficiency in the enzyme arylsulfatase A (ARSA), which leads to the accumulation of sulfatides in both the central nervous system and peripheral nervous system." (PMID 36329444, 2022). "Metachromatic Leukodystrophy (MLD) is a rare autosomal recessive disease, which is caused by mutations in the arylsulfatase A (ARSA) gene." (PMID 36324388, 2022). "Sulfatides (3-O-sulfogalactosylceramides as referred in this study) are the main sulfated glycolipids accumulating in Metachromatic Leukodystrophy (MLD), a genetic, lysosomal storage disease (LSD) caused by deficiency of aryl-sulfatase A (ARSA)." (PMID 35351138, 2022). "For example, metachromatic leukodystrophy (MLD) is caused by the deficiency of lysosomal enzyme arylsulfatase A (ARSA), which leads to the accumulation of sphingolipid sulfatide in the oligodendrocytes, causing oligodendrocytal degeneration and progressive demyelination." (PMID 35782737, 2022). "ARSA protein and gene therapy has been shown to be a safe therapeutic approach for metachromatic leukodystrophy in humans, and future studies are warranted to assess the potential for ARSA as a therapeutic strategy for the treatment of type 2 diabetes." (PMID 35273160, 2022). "Metachromatic leukodystrophy (MLD) is a lysosomal sphingolipid storage disorder inherited in an autosomal recessive manner and caused by genetic mutations in the ARSA gene." (PMID 35227276, 2022). "Related findings have been described for ASA (arylsulfatase A), the enzyme defective in the sister disease metachromatic leukodystrophy." (PMID 34172992, 2021). "Deficiency of arylsulfatase A (ARSA) (EC 3.1.6.8) (also due to pathogenic variants in ARSA or PSAP revealing metachromatic leukodystrophy [MLD; OMIM #250100] or SAP‐B deficiency [SAP‐B; OMIM #249900]) leads to accumulation of sulfatides causing neurodegeneration." (PMID 33728250, 2021). "Metachromatic leukodystrophy (MLD; OMIM 250100) is a rare, life‐limiting, autosomal recessive lysosomal storage disease (LSD) caused by deficient arylsulfatase A (ASA) activity." (PMID 33332761, 2021). "Metachromatic leukodystrophy (MLD, OMIM #250100) is due to mutations in ARSA (Arylsulfatase A), necessary for the metabolism of sulfatide, causing hypotonia, mental deterioration and cognitive regression." (PMID 32351971, 2020). "With the same end, in Metachromatic Leukodystrophy, hematopoietic stem cells transduced with the ARSA gene were useful for establishing the restoration of the biochemical metabolic defect and were also used as vehicle for the ARSA gene in patients affected." (PMID 32041088, 2020). "Metachromatic Leukodystrophy (MLD, OMIM 250100) is a neurodegenerative disease caused by mutations in the ARSA gene (OMIM 607574) that lead to deficiency in Arylsulfatase A (ASA)." (PMID 32431092, 2020). "Metachromatic leukodystrophy (MLD; OMIM 250100) is a rare, autosomal recessive lysosomal storage disease caused by a functional deficiency of the lysosomal enzyme arylsulfatase A (ASA or ARSA)." (PMID 31036045, 2019). "Metachromatic Leukodystrophy (MLD) is an autosomal recessive, monogenic disease caused by mutations in the arylsulfatase A (ARSA) gene, leading to deficiency of the enzyme ARSA and therefore inadequate degradation of sulfatides." (PMID 31186049, 2019). "Here, we generated human iPSC (hiPSC) clones via reprogramming of skin fibroblasts derived from normal donors and patients affected by metachromatic leukodystrophy (MLD), a fatal neurodegenerative lysosomal storage disease caused by genetic defects of the arylsulfatase A (ARSA) enzyme." (PMID 28191778, 2017).
metachromatic leukodystrophy (continued). "Genetic deficiency in the lysosomal enzymes arylsulfatase A (ARSA) and galactosylceramidase (GALC) causes metachromatic leukodystrophy (MLD) and globoid cell leukodystrophy (GLD or Krabbe disease), respectively." (PMID 27025653, 2016). "Metachromatic leukodystrophy (MLD) is a rare autosomal recessive lysosomal storage disease (LSD) caused by deficient activity of a lysosomal enzyme, arylsulfatase A (ASA)." (PMID 26283284, 2015). "Metachromatic leukodystrophy (MLD) is a rare autosomal recessive inherited disease, which is caused by a deficiency in the enzyme activity of Arylsulfatase A (ARSA)." (PMID 26553228, 2015). "Metachromatic leukodystrophy (MLD) is a rare, fatal, demyelinating lysosomal storage disease usually caused by deficient arylsulfatase A (ARSA) enzyme activity." (PMID 26245762, 2015). "It was first described in 1964 by Austin as an atypical form of metachromatic leukodystrophy (MLD), a disease caused by deficient arylsulfatase A activity." (PMID 25885655, 2015). "Other diseases that may be treated by microglial-targeted gene therapies include lysosomal storage diseases, such as metachromatic leukodystrophy (MLD) caused by deficiency of the enzyme for arylsulfatase A." (PMID 22800579, 2012). "This investigation shows an accumulation of the lysosphingolipid lysosulfatide in the brain of Arylsulfatase A deficient mice (ASA -/-), a murine model for the human disease Metachromatic Leukodystrophy (MLD)." (PMID 21299873, 2011). "Metachromatic leukodystrophy (MLD) is a rare, autosomal recessive disorder of lipid metabolism characterized by deficiency of arylsulfatase A (ARSA), which leads to an accumulation of sulfatides in central and peripheral nerve system and eventually to progressive demyelination." (PMID 41293478, 2025). "In metachromatic leukodystrophy, a mutation in the ARSA gene, encoding the lysosomal enzyme arylsulfatase A, results in the accumulation of sulfatides in multiple cell types, including SCs, leading to cytotoxicity and demyelination of most of the nerve fibers of the CNS and PNS." (PMID 40940747, 2025). "Metachromatic leukodystrophy (MLD) is a hereditary neurodegenerative disease characterized by demyelination and motor and cognitive impairments due to deficiencies of the lysosomal enzyme arylsulfatase A (ARSA) or the saposin B activator protein (SapB)." (PMID 37298156, 2023). "Metachromatic leukodystrophy (MLD), a rare inherited condition caused by arylsulfatase A (ARSA) deficiency, which results in the accumulation of fats (sulfatides) leading to the destruction of neurons and the protective fatty layer (myelin) surrounding the nerves in the brain and spinal cord." (PMID 37644601, 2023). "For example, metachromatic leukodystrophy (MLD) is a lysosomal storage syndrome that is promoted by deficiency of the enzyme arylsulfatase (ARSA; EC 3.1.6.8) and, in some cases, because of defects in the activity of the ARSA cofactor saposin B, both of which are required for sulfatide turnover." (PMID 36533082, 2022). "Heterozygosity for metachromatic leukodystrophy and an arylsulfatase A pseudodeficiency allele does not cause neurological or neuropsychiatric features." (PMID 35822086, 2022). "Metachromatic leukodystrophy (MLD) is a rare, autosomal recessive lysosomal storage disease caused by deficient activity of arylsulfatase A. Neurological involvement results in severe disability and premature death, but understanding of the natural history of the disease remains limited." (PMID 31036045, 2019). "Furthermore, there are many reports on the pseudodeficiency alleles on arylsulfatase A (ARSA), an enzyme responsible for metachromatic leukodystrophy." (PMID 28725570, 2017). "Metachromatic leukodystrophy (MLD) is a lysosomal storage disease resulting from a deficiency of arylsulfatase A causing an accumulation of cerebroside sulfate, a lipid normally abundant in myelin." (PMID 27079147, 2016).
metachromatic leukodystrophy (continued). "Metachromatic leukodystrophy (MLD) and globoid cell leukodystrophy (GLD or Krabbe disease) are severe neurodegenerative lysosomal storage diseases (LSD) caused by arylsulfatase A (ARSA) and galactosylceramidase (GALC) deficiency, respectively." (PMID 27025653, 2016). "Metachromatic leukodystrophy (MLD, OMIM #250100) is a rare lysosomal storage disorder caused by biallelic disease-causing variants in ARSA, the gene encoding arylsulfatase A (ASA), leading to decreased or absent activity of ASA." (PMID 40577679, 2025). "Metachromatic leukodystrophy (MLD, OMIM250100) represents an autosomal recessive (AR) form of leukodystrophy caused by pathogenic variants in ARSA gene." (PMID 41394098, 2025). "Leveraging QCL-MIR imaging-guided MSI workflows, we demonstrate this concept using arylsulfatase A-deficient (ARSA−/−) mice, a model of human metachromatic leukodystrophy (MLD)." (PMID 40404613, 2025). "Metachromatic leukodystrophy (MLD) represents a lysosomal storage disorder stemming from mutations within the ARSA gene, which encodes the arylsulfatase A enzyme." (PMID 39559557, 2024). "Interest in NBS for metachromatic leukodystrophy (MLD) and development of an assay for arylsulfatase A (ARSA) activity in DBS leukocytes using liquid chromatography tandem mass spectrometry LC MS/MS contributed to the development of a NBS testing algorithm." (PMID 38920845, 2024). "Metachromatic leukodystrophy (MLD) is an LSD caused by autosomal recessive mutations in ARSA, the gene coding for lysosomal hydrolase arylsulfatase A (ASA)." (PMID 33920837, 2021). "One of the sulfatases that MSD affects is arylsulfatase A, the defective enzyme in metachromatic leukodystrophy (MLD)." (PMID 32414121, 2020). "A retrospective study demonstrated that clinical symptoms in three families with ARSA haploinsufficiency (metachromatic leukodystrophy, or MLD) were similar to those described in PD patients with GBA1 mutations." (PMID 32674335, 2020). "Pathophysiological mechanisms proposed for DPHL have included Arylsulfatase A (ARSA) deficiency because of the histologic similarities between DPHL and metachromatic leukodystrophy, but subsequent studies showed ARSA deficiency to be neither necessary nor sufficient for the development of DPHL." (PMID 32993556, 2020). "Metachromatic leukodystrophy (MLD, OMIM #250100) is an autosomal recessively inherited sulfatide storage disease caused by deficient activity of the lysosomal enzyme arylsulfatase A (ASA)." (PMID 32632536, 2020). "Metachromatic leukodystrophy (MLD; OMIM #250,100) is a rare neurodegenerative disorder resulting in a deficiency of arylsulfatase A activity (ARSA, EC 3.1.6.8)." (PMID 31694723, 2019). "Metachromatic leukodystrophy (MLD, MIM 250100) is an autosomal recessively inherited metabolic disease caused by deficient activity of the lysosomal enzyme arylsulfatase A (ASA)." (PMID 31684987, 2019). "A first evidence comes from a study on metachromatic leukodystrophy (MLD), an LSD caused by mutations in the lysosomal hydrolase arylsulfatase A (ASA)." (PMID 31284546, 2019). "Metachromatic leukodystrophy (MLD, OMIM 250100) is an autosomal recessive lysosomal disorder caused by mutations in the ARSA gene." (PMID 29383515, 2018). "Recombinant human arylsulfatase A (rhASA) is in clinical development for the treatment of patients with metachromatic leukodystrophy (MLD)." (PMID 29672630, 2018). "Here we describe a cell-based assay using patient cell lines to identify small molecules that enhance the residual arylsulfatase A (ASA) activity found in patients with metachromatic leukodystrophy (MLD), a progressive neurodegenerative LSD." (PMID 22216298, 2011). "Metachromatic leukodystrophy (MLD) is an autosomal recessive inherited LSD (OMIM 250100) where the enzyme arylsulfatase A (ASA, EC." (PMID 21299873, 2011).